NAT9 (N-acetyltransferase 9)
Description:
N-acetyltransferase that mediates the acetylation of the N-terminal residues of alpha- and beta-tubulin.
Synonyms: DKFZP564C103; EBSP, hNATL
Tractability: PROTAC: ubiquitination databases record sites on it; its protein half-life has been measured.
Gene: Protein-coding gene on chromosome 17 (74,770,522 to 74,776,384, reverse strand). Ensembl gene ENSG00000109065.
Subcellular location (Human Protein Atlas): Nucleoplasm
Gene Ontology:
Molecular function: protein binding; tubulin N-terminal-methionine acetyltransferase activity; acyltransferase activity, transferring groups other than amino-acyl groups; N-acetyltransferase activity
Biological process: regulation of mitotic spindle assembly
Cellular component: protein-containing complex
Genetic constraint (gnomAD): Loss-of-function variants: 23 observed, 29.82 expected, observed/expected ratio (o/e) 0.77, 90% interval 0.55 to 1.09. The upper end of that interval is the gene's LOEUF score, 1.09, which puts it in group 4 of 6, group 1 being the genes least tolerant of losing a copy. Missense variants: 254 observed, 272.42 expected, observed/expected ratio (o/e) 0.93, 90% interval 0.84 to 1.03. Synonymous variants: 104 observed, 107.74 expected, observed/expected ratio (o/e) 0.97, 90% interval 0.82 to 1.14.
Homologues: Orthologues: chimpanzee NAT9 (99% identical), macaque NAT9 (91% identical), guinea pig NAT9 (87% identical), dog NAT9 (87% identical), pig NAT9 (86% identical), rat Nat9 (83% identical), mouse Nat9 (82% identical), tropical clawed frog nat9 (63% identical), zebrafish nat9 (55% identical), Drosophila melanogaster Mnat9 (46% identical), Caenorhabditis elegans Y67D2.5 (41% identical).
Diseases named in the same sentence as NAT9 in open-access papers:
NAT9 is named in the same sentence as 6 diseases in open-access papers, as found by Europe PMC text mining. Sharing a sentence is not in itself a finding about the gene and the disease. The quoted sentences say what the papers report.
psoriasis (4 papers, 2016 to 2023). An autoimmune condition characterized by red, well-delineated plaques with silvery scales that are usually on the extensor surfaces and scalp. "It was proposed that defective regulation of NAT9 may serve as a susceptibility factor for psoriasis (OMIM 177900), a chronic inflammatory skin disorder." (PMID 37507384, 2023). "The analysis highlighted interesting variants that may be implicated in psoriasis onset, including one in the NAT9 gene." (PMID 36902182, 2023). "NAT9, a hypermethylated and down-expressed gene in SA cows, encodes a new member of the N-acetyltransferase superfamily and has been reported to be a susceptibility factor for psoriasis, which is a chronic inflammatory skin disorder disease." (PMID 27411928, 2016). "Furthermore, misregulation of NAT9 may serve as a susceptibility factor for psoriasis and inflammation." (PMID 37507384, 2023). "We found variants already associated directly to psoriasis in the TRAF3IP2 gene, and interestingly we found a missense variant in the NAT9 gene." (PMID 36902182, 2023). "Moreover, aberrant expression of runt-related transcription factor 1 (RUNX1) has been implicated in defective regulation of sodium-hydrogen antiporter 3 regulator 1 (SLC9A3R1) and N-acetyltransferase 9 (NAT9) in both psoriasis and rheumatoid arthritis." (PMID 31402919, 2019).
mastitis (2 papers, 2020). Inflammation of breast tissue during lactation or postpartum due to an obstructed duct or infection. "The NRG1, MST1, and NAT9 genes are closely related with the progression of S. aureus subclinical mastitis and serve as epigenetic markers for improving mastitis resistance in dairy cows." (PMID 32000686, 2020). "Genome-wide DNA methylation analysis of peripheral blood lymphocytes identified 1,078 differentially methylated genes between cows with S. aureus-mastitis and healthy cows, as well as the potential of NRG1, MST1, and NAT9 genes to serve as biomarkers of S. aureus mastitis progression." (PMID 33193625, 2020).
viral infection (2 papers, 2023 to 2025). "The N-acetyltransferase Nat9 plays important roles during virus infection." (PMID 36695606, 2023). "Endoplasmic reticulum (ER)-resident N-acetyltransferase 9 (Nat9) interacts with porcine reproductive and respiratory syndrome virus (PRRSV) glycoprotein 5 (GP5) and targets GP5 for K27-linked polyubiquitination and proteasomal degradation, suppressing viral infection." (PMID 40307900, 2025).
Bovine mastitis (1 paper, 2016). INFLAMMATION of the UDDER in cows. "Further functional analysis revealed that three genes, NRG1, MST1 and NAT9, were strongly correlated with the progression of S. aureus subclinical mastitis and could be used as powerful biomarkers for the improvement of bovine mastitis resistance." (PMID 27411928, 2016).
cancer (1 paper, 2023). A tumor composed of atypical neoplastic, often pleomorphic cells that invade other tissues. "hNATs have also been implicated in cancer but the role of NAT9 in cancer remains unknown." (PMID 37507384, 2023).
NAT9 also shares sentences with these, for which no sentence is quoted: rheumatoid arthritis (1 paper).